EGF (epidermal growth factor)
Diseases named in the same sentence as EGF in open-access papers (continued):
Sharing a sentence is not in itself a finding about the gene and the disease.
cancer (continued). "It acts either as a negative or positive regulator in multiple cytokine/growth factor signaling pathways (e.g., EGF, TGF-β, NOD2, IL-17 family, etc.), modulating cancer development and inflammatory diseases including asthma." (PMID 37607012, 2023). "Previously, we discovered that autophagy-mediated EGF secretion contributed to the hyperactivation of EGFR signaling, thereby triggering resistance to anti-cancer treatment." (PMID 37165076, 2023). "Caveolin-dependent endocytosis of E-cadherin is required for disruption of cell–cell adhesion induced by EGF signalling, which is relevant to the EMT of cancer cells." (PMID 37132654, 2023). "We have given special attention to betulinic acid mediated regulation of JAK/STAT, VEGF, EGF/EGFR, TRAIL/TRAIL-R, AKT/mTOR and ubiquitination pathways in the inhibition of cancer." (PMID 36615262, 2022). "In The Cancer Genome Atlas (TCGA) database, we found MDK is the highest upregulated growth factor in different types of cancer, even higher than that of established growth factors such as VGF, EGF, and TGFB1." (PMID 35487917, 2022). "Several stimuli induce EMT in cancer cells including growth factors like TGF-β and EGF, hypoxia, ECM stiffness, cell-cell and cell-ECM interactions, and epigenomic factors." (PMID 35494005, 2022). "In cancer cells, the extracellular domain of NRP1 can interact with EGFR and promote the EGFR signaling cascade elicited upon EGF stimulation." (PMID 35347234, 2022). "EGF is one of the most abundant growth factors, promoting EMT during metastasis by binding to EGFR on the plasma membrane of cancer cells." (PMID 35884900, 2022). "Epidermal growth factor receptor (EGFR), as a receptor for epidermal growth factor (EGF) and transforming growth factor-α (TGF-α), has been found to facilitate the growth and aggressiveness of cancer cells." (PMID 34991599, 2022). "These pathways include JAK/STAT Signaling, Renin-Angiotensin Signaling, Molecular Mechanisms of Cancer, IL-8 Signaling, CXCR4 Signaling, LPS-Stimulated MAPK Signaling, EGF Signaling, PEDF Signaling, NF-κB Activation by Viruses, and B Cell Receptor Signaling." (PMID 34983392, 2022). "EGF and HER family receptors play a key role in many human cancers and overexpression of these receptors has been correlated with an increase in secretion of VEGF and stimulation of blood vessel formation." (PMID 36291938, 2022). "Several TKIs or anti-cancer drugs, including cabozantinib and gefitinib, can inhibit HGF/c-MET-, ANG-2/Tie-2-, and/or EGF/EGFR-mediated signaling." (PMID 35008398, 2022). "Other proangiogenic factors secreted by cancer cells include fibroblast growth factor (FGF) family, interleukin-8 (IL-8), epidermal growth factor (EGF) and platelet-derived growth factor (PDGF)." (PMID 35211123, 2022). "In HCC, the cooperation of EGF signaling and MYC has been shown to lead to aggressive cancer progression." (PMID 35406486, 2022). "Upon epidermal growth factor (EGF) binds to EGFR, it activates AKT-mediated cancer cell proliferation and metastasis." (PMID 35572726, 2022). "It binds several ligands including EGF, betacellulin (BTC) and TGF-α, controls cellular proliferation and invasion and is overexpressed in various cancer types." (PMID 36505413, 2022). "In conclusion, our works demonstrated that MNX1-AS1 as a pan-cancer upregulated lncRNA, reinforces the Warburg effect through facilitating the non-glycolytic actions of PKM2 in the cell nucleus in response to EGF." (PMID 36476366, 2022). "The activation of the EGF/EGFR signalling pathways facilitates the EMT process and enrichment of ALDH+/CD44 high cancer stem cells (CSCs)-like cells with increased invasiveness/metastasis potentials both in vitro and in vivo." (PMID 35681586, 2022). "Common growth factor receptor pathways present in cancer cells, including HER2, IGF1 and EGF, can also contribute to upregulation of VEGF production and consequently increased angiogenesis." (PMID 36291938, 2022).
cancer (continued). "These cells secrete several factors (e.g., VEGF, PDGF, epidermal growth factor-EGF, prostaglandin, matrix metalloproteinases (MMP)), responsible for promoting cancer growth, lymphangiogenesis, angiogenesis, and consequent dissemination." (PMID 37386584, 2022). "Recently, it was suggested that differentiated cancer cells or progenitor cells can revert to CSCs through the cancer cell niche signals like WNT and EGF." (PMID 35359953, 2022). "We previously showed that PRELP gene overexpression inhibits cancer progression by blocking TGF-β and EGF pathways, reversing EMT, activating cell adhesion, and inhibiting various oncogenic pathways." (PMID 36371227, 2022). "CXCR2 activation also results in the secretion of epidermal growth factor (EGF) by epithelial cells, VEGF via STAT3 activation, and lymphangiogenic factors such as VEGF-C and VEGF-D by cancer cells." (PMID 35216283, 2022). "Endogenous EGF and other HER ligands are present in cancers and can rescue cells during HER-targeted therapy." (PMID 36009461, 2022). "L-Thyroxine (T4), steroid hormones, and epidermal growth factor (EGF) up-regulate the accumulation of checkpoint programmed death-ligand 1 (PD-L1) and promote inflammation in cancer cells." (PMID 35705962, 2022). "RCC tissues that successfully generated organoids highly expressed genes associated with stemness (WNT6/11, FZD8/9 and JAG2), cell matrix (MMP2, COL1A1), fatty metabolism (ACOT2, LIPE) and cancer development (TGFB1, SMAD6/7, EGF and FGF1)." (PMID 35802820, 2022). "Ligand activation of EPHA2 or EPHA2 knockdown by small interfering RNA inhibited EGF-induced cell motility of EGFR-overexpressing human cancer cells, indicating a functional role of EPHA2 in EGFR-expressing cancer cells." (PMID 36297233, 2022). "Reportedly, exPKM2 can activate the epidermal growth factor receptor (EGFR) signaling pathway in cancer cells, and EGFR ligands, including EGF and transforming growth factor-α, can enhance bone resorption." (PMID 35256696, 2022). "Many new chemical structures were designed and synthesized regarding cancer’s biological targets, such as cyclin-dependent kinase (CDK), epidermal growth factor (EGF), Ras, and tubulin proteins." (PMID 36551271, 2022). "TME cells secrete a variety of pro-inflammatory cytokines that interfere with anti-cancer immune response (VEGF), interleukins (IL-6, IL-12), epidermal growth factor (EGF), as well as tumor necrosis factor-alpha (TNF-a) and indoleamine-2,3-dioxygenase (IDO)." (PMID 35743107, 2022). "Epidermal growth factor (EGF), tumor necrosis factor-α (TNF-α), and Wnt signals are reported to cooperate with TGF-β signaling during cancer progression." (PMID 36140527, 2022). "The results showed that T cells with high expression of CD161 interacted closely with cancer cells through signal pathways such as ANGPTL, BMP, EGF, FGF, SEMAS, and WNT." (PMID 36660546, 2022). "EGFR-targeting nanobodies have been isolated by phage display, also in competition with other specific ligands (i.e., EGF or cetuximab), leading to the identification of several excellent scaffolds that have been used to target EGFR-overexpressing cancers." (PMID 35213974, 2022). "We additionally illustrated that the regulation network of EGF-AKT signaling in stabilizing CHD6, and consequent accumulation of TMEM65 during cancer formation can be blocked by Cetuximab treatment." (PMID 36473865, 2022). "Epidermal growth factor (EGF) signalling regulates normal epithelial and other cell growth, with EGF receptor (EGFR) overexpression reported in many cancers." (PMID 35612280, 2022). "CAFs are involved in the growth of HCC by producing epidermal growth factor (EGF), hepatocyte growth factor (HGF), and fibroblast growth factor (FGF), which act on adjacent cancer cells and promote rapid proliferation." (PMID 35248060, 2022).
cancer (continued). "Enhancement of epidermal growth factor (EGF) has been found to upregulated genes involved in the IGF-1 and Wnt signaling pathways, resulting in that A promoting cancer cell proliferation." (PMID 35886904, 2022). "As its scale continues to expand, cancer cells need to secrete growth factors such as VEGF, EGF, and ECF to promote the formation of blood vessels around them, thereby increasing the efficiency of nutrient transport." (PMID 35401748, 2022). "FUT8 is frequently upregulated in cancer, and plays a critical role in immune evasion, antibody-dependent cellular cytotoxicity (ADCC), and the regulation of TGF-β, EGF, α3β1 integrin and E-Cadherin." (PMID 33466384, 2021). "EGF activates the mitochondrial translocation of EGFR, mitochondrial fission, and redistribution, upregulates cellular ATP production, and enhances cancer cell motility in vitro and in vivo." (PMID 33498743, 2021). "Excitation of the EGF/EGFR signaling pathway promotes the proliferation and invasion of cancer cells." (PMID 33980265, 2021). "HER2 plays an important role in regulation of complex intracellular pathways in response to biochemical stimuli such as epidermal growth factor (EGF) and transforming growth factor (TGF-β) for critical decision of cell fate within cancer cells." (PMID 34669701, 2021). "In HCC, as in other types of cancer, VEGF shares common pathways with EGF, IGF-1, and HGF, such as MET, EKT, or Akt, among others." (PMID 34572344, 2021). "For example, HAS mRNA transcription can be stimulated by epidermal growth factor (EGF), keratinocyte growth factor (KGF), and PDGF in keratinocytes, and these growth factors are frequently overexpressed in cancer." (PMID 33888679, 2021). "Previous studies have shown that the epidermal growth factor receptor (EGFR) ligands epidermal growth factor (EGF) and transforming growth factor-α (TGF-α) transactivate the GPER promoter and stimulate its expression in cancer cells." (PMID 34773076, 2021). "For instance, epidermal growth factor (EGF) is a ligand of EGFR, a proto-oncogene that activates downstream kinases, such as FAK, to regulate cell adhesion site dynamics, thus promoting cancer growth, migration, and metastasis." (PMID 33854965, 2021). "Ingenuity pathway analysis of the list of genes differentially expressed between Ctrl -EGF and WDR73 KD -EGF conditions, revealed that the category of functions the most significantly enriched in the WDR73 KD -EGF condition was cancer." (PMID 33686175, 2021). "As EGF-EGFR signaling has been implicated as a central channel in the development of multi-aggressive phenotypes by SCP3, we believe that inhibition of EGFR signaling may be an effective strategy to control refractory cancer, especially if there is high SCP3 expression." (PMID 34445562, 2021). "For example, CAFs secrete epidermal growth factor (EGF), insulin-like growth factor 2 (IGF2), and fibroblast growth factor 4 (FGF4), which increase not only the proliferation but also the survival of cancer cells after irradiation." (PMID 34135469, 2021). "Binding of epidermal growth factor to its receptor triggers EGFR autophosphorylation and drives a complex intracellular signal transduction pathway, which modulates a set of cancer-related phenotypes." (PMID 35052426, 2021). "In detail, peritoneal macrophages support angiogenesis and cancer growth through the production of vascular endothelial growth factor (VEGF) and epidermal growth factor (EGF)." (PMID 33722297, 2021). "The mechanism of GPCR involved in this cancer is the indirect activation of epidermal growth factor receptor (EGFR), by the release of epidermal growth factor (EGF) ligands from the surface which activates the intracellular signalling pathways." (PMID 33991433, 2021).
cancer (continued). "Numerous cancer targets including VEGF, FGF, PGF, EGF, PDGF, topoisomerase I and II, histone deacetylase, tyrosine kinase, and transforming growth factor-alpha (TGF-α) have been elucidated with multiple studies focused mainly on targeting the initiator VEGF." (PMID 34885716, 2021). "As expected, the expressions of key enzymes involved in glycolysis were all increased by administration of EGF but all decreased by administration of Wortmannin, implying that the activation of PI3K/ATK facilitates the progression of cancer." (PMID 33377619, 2021). "KCC4-specific siRNA significantly attenuated endogenous cellular invasiveness of cancer cells, and the residual cellular invasiveness was much less sensitive to IGF-1 or EGF stimulation." (PMID 35008759, 2021). "This interaction is further promoted by a positive feedback loop whereby cancer cells produce CSF1 and TAMs express epidermal growth factor (EGF) which is a positive regulator of RhoA signaling." (PMID 34803925, 2021). "KEGG analysis identified adhesion, hematopoiesis and cancer-related proteoglycans as affected pathways (e.g. metformin: CD9, CTSL, IL5, HGF; insulin: EGF, EZR, PLCG2, TFRC)." (PMID 33690729, 2021). "These phosphorylated tyrosine residues are bound to several adapter proteins, the EGF/EGFR signaling pathway is activated, which plays a critical role in cancer cells proliferation." (PMID 32901097, 2021). "Epidermal growth factor (EGF), a specific ligand for epidermal growth factor receptor (EGFR), which is also overexpressed in cancer cells, showed its potential for target delivery." (PMID 34064297, 2021). "EGF and TGF-α are peptides that regulate cell growth and are both thought to be involved in cancer development." (PMID 34887933, 2021). "The bioactivity of the mutant EGF-conjugates in terms of ERK activation and growth inhibition of cancer cells were also determined to verify the present strategy to improve anti-cancer effect of EGF-GNP conjugates." (PMID 34512175, 2021). "EGF also increases matrix metalloproteinase 9 (MMP9) activity, which plays a role in cancer progression, cancer invasion and metastasis." (PMID 34115785, 2021). "Cav1 was reported to block EGF-mediated proliferation, migration and invasion by targeting downstream effectors (mainly MEK/ERK and Pi3K/AKT/mTor) in various cancers." (PMID 34207120, 2021). "The release of EGF and TGF-β enhances the intravasation process by allowing the cancer cells to cross blood vessels barriers." (PMID 33546106, 2021). "Signals of epidermal growth factor (EGF), insulin-like growth factor (IGF)-1, and transforming growth factor (TGF)-β crosstalk with integrin αvβ3 stimulate cancer cell proliferation." (PMID 34359854, 2021). "To date, the limited evidence on HGF, EGF, and IGF-1 and their effect on liver regeneration seems to support a beneficial effect on the regeneration process or in cancer recurrence." (PMID 34572344, 2021). "Because aberrant activation of the Wnt–β-catenin and/or EGF–RAS pathways are frequently observed in various types of cancers, ARL4C is indeed expressed in a number of cancers." (PMID 34590580, 2021). "As the point at which EGF signaling and the energetic stress response converge, the GSK3β–SIRT7 axis represents an ideal therapeutic target in various cancers." (PMID 34433808, 2021). "Immune evasion and growth factor dependence are two hallmarks of cancer, which can be targeted by ICI and CIMAavax-EGF or anti-EGFR MAbs." (PMID 34211836, 2021). "Growth factors such as epidermal growth factor (EGF) can trigger HD disassembly and induce the phosphorylation of integrin β4 intracellular domains, which mediate invasion in carcinoma cells." (PMID 34439865, 2021).
cancer (continued). "Here we review the epidermal growth factor (EGF), which controls epithelial cells, the precursors of all carcinomas, and the cognate cell surface receptor, called EGFR." (PMID 34206026, 2021). "Invadopodia are spatially complex structures formed in cancer cells under the influence of the TME, whereby in addition to TGF-β, HGF and epidermal growth factor (EGF), hypoxia in particular stimulates their formation." (PMID 33379400, 2020). "In some studies, the EGF/EGFR signaling pathway has been known to contribute significantly to the formation and maintenance of CSCs in various cancer." (PMID 32376896, 2020). "As a member of the epidermal growth factor (EGF) receptor family, ERBB2 overexpression and activation in cancer metastasis have been well recognized." (PMID 33042286, 2020). "Functional in vitro assays with purified MDSCs revealed that the TGF-β, epidermal growth factor (EGF) and HGF signaling pathways were all involved in MDSC-induced EMT activation of cancer cells." (PMID 35582229, 2020). "A431 cells, which are considered model EGFR-overexpressing cancer cells, were treated with TiO2 PEG NPs and EGF-TiO2 PEG NPs, then the localization of EGFR was visualized by immunofluorescence staining." (PMID 33003324, 2020). "Of these 4 biomarkers, ARL4C is a transcriptional factor induced by cooperative signaling of Wnt/β-catenin and EGF/Ras-MAPK signaling activation, which promotes proliferation, migration, and invasion of cancer cells." (PMID 33092599, 2020). "Some of the vital CAF-activating factors released by cancer cells are TGF-β, PDGF, IL-6, IL-1β, epidermal growth factor (EGF), and lysophosphatidic acid (LPA)." (PMID 33066013, 2020). "These suggested that GALNT7 promoted cancer development by activating the JAK-ATAT or CAMs signaling pathway.Earlier studies also showed that EGF was involved in cell proliferation through activating the EGF receptor (EGFR) signaling pathway." (PMID 32308562, 2020). "In cancer, SIRT1 is upregulated during EGF-mediated epithelial-to-mesenchymal transition, while in vascular smooth muscle cells, resveratrol, a SIRT1 stimulator, interferes with EGF-induced ROS production." (PMID 32106619, 2020). "Whereas EGF is a strong mitogen for follicular thyroid cells, TGF-β has a complicated role in cancer." (PMID 32033410, 2020). "The presence of surface EGF allows EGF-PLGA@5Fu/PFC NPs to interact strongly with EGFR, which results in anchoring of these NPs to cancer cells that express high levels of EGFR." (PMID 32345258, 2020). "CSC promote cancer angiogenesis via several mechanisms include: over-expression of several angiogenic factors, such as VEGF, angiopoietin, EGF." (PMID 32788883, 2020). "To address this question, we measured the viabilities of cancer cells, MGC‐803 and PC‐9, after they were treated with different cytokines or EGF for 3 days." (PMID 32323422, 2020). "Further investigation is needed to fully understand the roles of EGF and TGF-β in primary cultures of cancer tissue." (PMID 33235257, 2020). "These stress neurotransmitters activate β-adrenergic receptors to stimulate the release of EGF, leading to activated EGFR signaling cascade and the development and progression of numerous cancers." (PMID 32957649, 2020). "Our findings suggest that EGF conjugation increases the uptake level and decreases the cell proliferative effect of TiO2 PEG NPs by EGFR-overexpressing cancer cells." (PMID 33003324, 2020). "Signals including the epidermal growth factor (EGF), transforming growth factor beta 1 (TGF-β1), and thrombospondin 1 mediate the proliferation and quiescence of cancer cells during dissemination." (PMID 31900168, 2020).